CALCA (calcitonin related polypeptide alpha)
Diseases named in the same sentence as CALCA in open-access papers (continued):
Sharing a sentence is not in itself a finding about the gene and the disease.
tumor (continued). "Furthermore, among the receptor-ligand pairs between tumor cells and DC, the CALCA-CALCRL pair was the most significantly upregulated in MTC compared to PTC." (PMID 39030177, 2024). "It is worth noting that in the rescue experiment, we treated CALCA-overexpressed pNETs cells with the mTOR agonist MHY1485, which could significantly reverse the proliferation inhibition induced by CALCA overexpression and promote tumor growth and angiogenesis." (PMID 41281753, 2025). "Thus, the abnormal methylation level of CALCA fragment in the promoter region of stem cells is an important reason for the change of cell stemness, and high-methylation phenotype is also an important biomarker in the process of tumor diagnosis and treatment." (PMID 35132349, 2022). "Intriguingly, MTC tumor cells had a strong CALCA-CALCRL interaction with DCs but such interaction did not occur on either themselves or with T cells." (PMID 39030177, 2024). "Mutations of CALCA (calcitonin) and the corresponding receptor CALCAR were found in all five tumor samples, but none of them resulted in protein sequelae or clinical relevance." (PMID 37771441, 2023). "Some peptidergic genes such as CALCA and GRP that are expressed in almost all normal PNECs were expressed in few if any tumor cells, whereas NPW, NMB, and CARTPT that are expressed in only rare PNECs were expressed in most (NPW) or many (NMB, CARTPT) of the tumor cells." (PMID 36469459, 2022). "Differential gene expression analysis revealed elevated expression of CALCA (preprocalcitonin) and CCDC183 (highly expressed in testes) in patients who experienced clinical activity, suggesting that tumor neoantigens from these genes may contribute to immune response." (PMID 37038005, 2023). "Similarly, our findings also showed that 3 of 6 genes had significantly higher methylation level in tumor tissues than nonmalignant lung tissues, including CALCA, CDH1, and PAX6 genes." (PMID 21639921, 2011). "We tested the promoter methylation of CCND2, CCNA1 and CALCA in urine sediment DNA from primary UCC cases and subjects without any neoplastic disease (controls/normals)." (PMID 24980822, 2014).
CALCA also shares sentences with these, for which no sentence is quoted: Bacterial infection (6 papers); colitis (3); osteoporosis (3); Stroke (3); testicular germ cell tumor (3); adenocarcinoma (2); Arthritis (2); psoriasis (2); thyroid nodule (2); acute leukemia (1); acute pancreatitis (1); acute tubular necrosis (1); airway hyperresponsiveness (1); allergic asthma (1); angina (1); aortic aneurysm (1); asthma (1); atherosclerosis (1); benign tumors (1); cardiovascular disease (1); co-infection (1); concussion (1); Crohn disease (1); emphysema (1); endotoxemia (1); Erythema (1); fetal growth restriction (1); gastritis (1); glioblastoma (1); hematological cancers (1).
A further 30 diseases each share a sentence with CALCA in 1 paper.